AFF1 (ALF transcription elongation factor 1)
Synonyms: AF4; FEL; MLLT2; PBM1; AF-4
Tractability: PROTAC: ubiquitination databases record sites on it; its protein half-life has been measured.
Gene: Protein-coding gene on chromosome 4 (86,934,237 to 87,141,073, forward strand). Ensembl gene ENSG00000172493.
Subcellular location: Nucleus
Subcellular location (Human Protein Atlas): Mitochondria; Nucleoplasm
Gene Ontology:
Molecular function: protein binding; transcription elongation factor activity; transcription coregulator activity
Biological process: DNA damage response; DNA-templated transcription elongation; positive regulation of DNA-templated transcription, elongation; positive regulation of transcription elongation by RNA polymerase II; nervous system process; regulation of DNA-templated transcription; regulation of gene expression
Cellular component: chromatin; nucleus; site of DNA damage; super elongation complex; transcription elongation factor complex
Genetic constraint (gnomAD): Loss-of-function variants: 45 observed, 117.75 expected, observed/expected ratio (o/e) 0.38, 90% interval 0.3 to 0.49. The upper end of that interval is the gene's LOEUF score, 0.49, which puts it in group 2 of 6, group 1 being the genes least tolerant of losing a copy. Missense variants: 1,490 observed, 1,547.3 expected, observed/expected ratio (o/e) 0.96, 90% interval 0.92 to 1. Synonymous variants: 608 observed, 581.89 expected, observed/expected ratio (o/e) 1.04, 90% interval 0.98 to 1.12.
Homologues: Orthologues: chimpanzee AFF1 (99% identical), macaque AFF1 (97% identical), dog AFF1 (82% identical), rabbit AFF1 (81% identical), pig AFF1 (78% identical), mouse Aff1 (73% identical), rat Aff1 (72% identical), guinea pig AFF1 (67% identical), tropical clawed frog aff1 (46% identical), Drosophila melanogaster lilli (21% identical). Paralogues in human: AFF4 (37% identical), AFF3 (31% identical), AFF2 (30% identical).
Diseases named in the same sentence as AFF1 in open-access papers:
AFF1 is named in the same sentence as 77 diseases in open-access papers, as found by Europe PMC text mining. Sharing a sentence is not in itself a finding about the gene and the disease. The quoted sentences say what the papers report.
leukemia (162 papers, 2009 to 2026). A malignant (clonal) hematologic disorder, involving hematopoietic stem cells and characterized by the presence of primitive or atypical myeloid or lymphoid cells in the bone marrow and the blood. "Our findings suggest that the loss of SMAD1 in KMT2A-rearranged leukemia with KMT2A::AFF1 promotes tumor growth." (PMID 39834944, 2024). "Having identified differential enhancer usage in KMT2A::AFF1 leukemias, we wanted to explore what might be causing these differences." (PMID 40729681, 2025). "Lineage switching of leukemias may also occur; for example, leukemia associated with the KMT2A/AFF1 fusion gene, which commonly presents as pediatric B cell precursor ALL, may also demonstrate an infant B/myeloid mixed phenotype or relapse with the original clone switching to AML." (PMID 35409034, 2022). "Infants and children with KMT2A::AFF1+ leukemia have a dismal prognosis and are therefore in urgent need for more efficient and less aggressive therapy." (PMID 42038742, 2026). "In particular, KMT2A::AFF1 ALL, an aggressive leukemia with a poor prognosis and a low mutational burden, exhibits substantial transcriptional heterogeneity between individuals." (PMID 40729681, 2025). "In KMT2A::AFF1 rearranged leukemia, DOT1L-binding and consequent H3K79me was reported at a subset of enhancers." (PMID 40781484, 2025). "Here, we present a novel murine KMT2A::AFF1 model, that provides key insights into KMT2A::AFF1 pre-leukemia, relevant to human disease." (PMID 40646135, 2025). "In connection with these data, KMT2A::AFF1 fusion protein promotes leukemia progression mainly by activating pro-leukemogenic factors HOXA9 and MEIS1." (PMID 40722046, 2025). "In keeping with these findings, FACS CD133+CRISPRKMT2A::AFF1 blasts underwent ∼100-fold higher expansion in vitro compared to CD133– blasts from the same leukemia." (PMID 40609078, 2025). "We therefore explored expression of HMGA2 in different sub-types of ALL, and found it upregulated in KMT2A::AFF1-driven leukemia and enriched in infants." (PMID 40646135, 2025). "This approach uncovered a distinct fetal pre-leukemic state and identified a transcriptional signature transferable to human KMT2A::AFF1 leukemia." (PMID 40646135, 2025). "NSG mice developing primary CD133+CRISPRKMT2A::AFF1 leukemia (n = 4) had significantly shorter survival than mice developing CD133– (n = 12) leukemia (119 vs 140.7 days median, P = .0004)." (PMID 40609078, 2025). "PROM1 KO or Cas9-only control CRISPRKMT2A::AFF1 blasts were also transplanted into NSG mice 12 to 18 hours after KO (n = 2 CRISPRKMT2A::AFF1 leukemias, 12 mice)." (PMID 40609078, 2025). "Certain fusion genes are associated with distinct subtypes of leukemia such as KMT2A::AFF1 and KMT2A::MLLT3 (also known as MLL-AF4 and MLL-AF9, respectively)." (PMID 39858509, 2025). "Combining menin inhibitors with depletion of IGF2BP3 impairs cell growth and increases differentiation of KMT2A::AFF1 leukemia." (PMID 38601080, 2024). "Depletion of the murine paralog IGF2BP3 increases the latency of leukemia in murine models of KMT2A::AFF1 AML." (PMID 38601080, 2024). "Genetic screening of bone marrow for 57 types of leukemia identified a positive KMT2A/AFF1 fusion gene." (PMID 39717192, 2024). "Of note, specific exons (KMT2A exon 7, and AFF1 exons 2 and 7) backspliced to generate the most abundant circRNAs of these genes in normal blood cells are also used in f-circRNAs produced by leukemia cells with rearranged genomes." (PMID 36585787, 2023). "In leukemia with KMT2A::AFF1 (MLL::AF4) fusions, we previously reported specific alterations of circRNA expression, but nothing was known about f-circRNAs." (PMID 36585787, 2023). "The second highlight of this study came from the investigation of leukemia with the KMT2A::AFF1 (MLL::AF4) fusion." (PMID 36585787, 2023).
leukemia (continued). "In infants with B ALL (<1 year of age), initial KMT2A rearrangements (particularly KMT2A/AFF1 gene fusions) in utero appear to be sufficient for the onset of leukemia before or shortly after birth, although secondary mutations are present in some cases." (PMID 35409034, 2022). "AFF1 is frequently fused with MLL (Mixed Lineage Leukemia) via chromosomal translocation, giving rise to MLL-AFF1 fusion protein in infant acute lymphoblastic leukemia (ALL)." (PMID 33493519, 2021). "Importantly, using a drug-repurposing approach, we found that inhibition of CA5B, PPP3CA, and PP2A by acetazolamide, tacrolimus, and LB-100, respectively, showed high toxicity toward KMT2A::AFF1+ leukemic blasts and reduced leukemia burden in vivo." (PMID 42038742, 2026). "Beyond leukemia, recent transcriptomic studies and single-cell analyses have shown that AFF1 is expressed in various tissues, including immune and hepatic tissues, and may participate in immune regulation, cellular signaling, and inflammation." (PMID 40823550, 2025). "To determine whether enhancer heterogeneity is an intrinsic feature of KMT2A::AFF1 leukemia or simply a reflection of the mutational differences between these cell lines, we wanted to use a genetically uniform system for deriving a KMT2A::AFF1 leukemia." (PMID 40729681, 2025). "The pattern of CD133 expression in CRISPRKMT2A::AFF1 leukemias was variable, as in patient samples." (PMID 40609078, 2025). "Importantly, the MI revumenib was approved by FDA for the treatment of KMT2A:AFF1-rearranged leukemia before our study was completed." (PMID 40722046, 2025). "Although MLL fuses with a variety of partners, most MLL fusion-mediated leukemia cases are caused by the fusions with the AF4 family (e.g., AF4 also known as AFF1, AF5Q31 also known as AFF4) and ENL family (e.g., ENL also known as MLLT1, AF9 also known as MLLT3)." (PMID 34431785, 2021). "Additionally, we showed that a TCR targeting KMT2A::AFF1 could contribute to leukemia control in vivo against the autologous tumor." (PMID 40707674, 2025). "We could speculate the existence of a clone with the KMT2A/AFF1 fusion, which competes with the NRAS-mutated clone and initiates the leukemic process, and a minor, which may accelerate the development of the overt leukemia." (PMID 34575904, 2021). "In summary, we have demonstrated that the novel IPI inhibitor M3258 is comparable to Btz in its anti-leukemia activity and that IPIs and Btz induce death of KMT2A::AFF1 expressing ALL cells through proteotoxic stress pathways." (PMID 40389585, 2025). "In leukemia, the KMT2A gene is often translocated and fused to AFF1 (also known as AF4), MLLT1 (also known as ENL), or MLLT3 (also known as AF9)." (PMID 38426219, 2024). "Although there are > 70 documented fusion partners of MLL1, transcription cofactors AF4 (also known as AFF1) and its paralog AFF4, AF9 and its paralog ENL, and ELL are found in > 70% MLL1-r leukemias." (PMID 33823889, 2021). "Given that KMT2A-R ALL is often a monoallelic balanced translocation with wild-type KMT2A and AFF1 still present in the cells, we then analyzed a ChIP-Seq data set that used human KMT2A-R leukemia cells generated via overexpression of a KMT2A-Aff1-flag construct." (PMID 40148558, 2025). "Here, we induced chromosomal translocations between the KMT2A and AFF1 genes in primary human UCB HSPCs to model (t;411) leukemia and performed multiomics analyses on the resultant gene-edited BCP-ALLs in comparison with patient ALLs and normal bone marrow from healthy donors." (PMID 37917159, 2024). "In the current study, to identify new potential molecular mechanisms characterizing KMT2A/AFF1+ B-ALL, we investigated, for the first time, the case of monozygotic twins with the discordant diagnosis of KMT2A/AFF1 leukemia by exploiting different “-omics” approaches." (PMID 34575904, 2021).
leukemia (continued). "The AFF1 recurrent breakpoint region position in MLLre leukemias reveals that this circAFF1 will likely not be generated from the chimeric gene." (PMID 30815012, 2019). "However, in the scope of this study we only show this in the KMT2A::AFF1 AML (MV4-11) model, which restricts the impact of our findings and does not allow for extrapolation to other KMT2A:.AFF1 harboring leukemias." (PMID 39834944, 2024). "Understanding whether the H3K4 trimethylation activity of KMT2B is disturbed in KMT2A-rearranged leukemia, and particularly in context with KMT2A::AFF1 and KMT2A::MLLT3 fusion genes, represents an intriguing next chapter in illuminating the pathobiology of KMT2A-rearranged leukemia." (PMID 39834944, 2024).
acute lymphoblastic leukemia (58 papers, 2009 to 2026). Leukemia with an acute onset, characterized by the presence of lymphoblasts in the bone marrow and the peripheral blood. "AFF1 at chr4q21.3 (lead SNP: rs236985) encoded a member of the AF4/ lymphoid nuclear protein and have been reported to be implicated in human childhood lymphoblastic leukemia." (PMID 38704398, 2024). "Curiously, AFF1 can also be strongly linked to cancer, as the chromosomal translocation of this locus generates fusion proteins associated with acute lymphoblastic leukaemia." (PMID 37509532, 2023). "In this study, we investigated three microRNAs that are downregulated in KMT2A::AFF1+ B-cell precursor acute lymphoblastic leukemia (BCP-ALL): miR-194, miR-99b, and miR-125a-5p." (PMID 42038742, 2026). "AFF1 is best known for its role in hematological malignancies, especially acute lymphoblastic leukemia (ALL), where chromosomal translocations involving AFF1 (such as MLL-AF4 fusion) lead to leukemogenesis." (PMID 40823550, 2025). "The most relevant advances have come from oncology, where efforts have focused on disrupting the MLL-AF4 fusion protein or modulating AFF1-driven transcriptional complexes in acute lymphoblastic leukemia." (PMID 40823550, 2025). "This study identified EGR3 as a regulator of B-lineage specification and commitment processes in the context of infant KMT2A::AFF1 acute lymphoblastic leukemia." (PMID 37100882, 2023). "Using CircFusion, we identified for the first time f-circRNAs in acute lymphoblastic leukemia with KMT2A::AFF1 translocation." (PMID 36585787, 2023). "We defined the landscape of aberrant fusion circular RNAs in infant acute lymphoblastic leukemia with KMT2A::AFF1 translocations." (PMID 36585787, 2023). "In acute lymphoblastic leukaemia, the down-regulation of AFF1 by miR-143 has induced apoptosis and suppressed leukemic cells growth." (PMID 26260454, 2015). "The AFF (AF4 (ALL1 (acute lymphoblastic leukemias)-fused gene from chromosome 4)/FMR2 (fragile X mental retardation 2)) family of genes includes four members: AFF1/AF4, AFF2/FMR2, AFF3/LAF4 and AFF4/AF5q31." (PMID 25268620, 2014). "In addition, the AFF1 gene was found to be downregulated in melanoma tissue and dysregulated in acute lymphoblastic leukemia." (PMID 31892232, 2019). "AFF1 is known to be involved in cytogenetic translocations of acute lymphoblastic leukemia (ALL)." (PMID 22291604, 2012). "Infant Acute Lymphoblastic Leukemia (ALL) driven by the KMT2A::AFF1 onco-fusion is an aggressive, poor prognosis disease with few co-operative mutations." (PMID 40646135, 2025). "Subsequent studies in KMT2A, AFF1-mature acute lymphoblastic leukemia (ALL) confirmed that M3258 induces proteotoxic stress and apoptosis, similar to bortezomib, but possibly with reduced off-target toxicities." (PMID 41293269, 2025). "Translocation of the KMT2A gene, better known as the MLL gene, is present in 7–10% of B acute lymphoblastic leukemias, AFF1 (or AF4) being the most frequent partner gene." (PMID 28535805, 2017). "The AFF (AF4/FMR2) family of genes includes four members: AFF1 (or AF4, acute lymphoblastic leukemia-1 fused gene from chromosome 4), AFF2 (or FMR2, Fragile X mental retardation 2), AFF3 and AFF4 (or AF5Q31, acute lymphoblastic leukemia-fused gene from 5q31)." (PMID 26214578, 2015). "We present a case of pro-B-cell acute lymphoblastic leukemia (ALL) with hyperleukocytosis in a 6-month-old infant, characterized by a positive KMT2A/AFF1 fusion gene with a leukocyte count of 1,755 × 109/L." (PMID 39717192, 2024).
acute myeloid leukemia (17 papers, 2012 to 2026). Acute myeloid leukemia (AML) is a group of neoplasms arising from precursor cells committed to the myeloid cell-line differentiation. "Overall, our data contributes to the understanding of the role of TGF-β signaling in acute myeloid leukemia with KMT2A::AFF1 by showing that SMAD1 loss can influence the growth dynamics and contribute to the pathogenic expression of disease driving factors." (PMID 39834944, 2024). "Blinatumomab has shown promising therapeutic results in refractory or relapsed B-ALL; however, it has potential risk of inducing lineage switch, especially in KMT2A/AFF1 rearranged B-ALL into acute myeloid leukemia and/or myeloid sarcoma." (PMID 31885955, 2019). "In particular, since KMT2A::AFF1 is the most common fusion among KMT2A-r ALL6,7, the majority of lineage-switched acute myeloid leukemia (LS AML) cases develop from KMT2A::AFF1 rearranged ALL2." (PMID 40858576, 2025).
acute leukemia (16 papers, 2013 to 2026). A clonal (malignant) hematopoietic disorder with an acute onset, affecting the bone marrow and the peripheral blood. "The most frequently found fusion partners of KMT2A in acute leukemia are the C‐terminal parts of AFF1, MLLT3, MLLT1 and MLLT10." (PMID 39887730, 2026). "We discovered and validated novel f-circRNAs in acute leukemia harboring KMT2A::AFF1 rearrangements, leading the way to future functional studies aimed to unveil their role in this malignancy." (PMID 36585787, 2023). "This correlates with the analysis of the KMT2A recombinome in acute leukemia and its distribution in clinical subgroups where AFF1 is the most frequent KMT2A rearrangement in ALL present in infant, pediatric, and adult patients." (PMID 35685921, 2022). "Nearly 135 different MLL rearrangements have been found in acute leukemias, which mostly include AF4 (AFF1), AF9, and ELN." (PMID 34372899, 2021). "It has been well established that fusion of AFF1 with MLL is one of the driving forces of infant acute leukemia with poor prognosis." (PMID 33493519, 2021). "Importantly, in this case study, we report the discovery with this software tool of new f-circRNAs in acute leukemia harboring KMT2A::AFF1 rearrangements." (PMID 36585787, 2023).
melanoma (5 papers, 2013 to 2024). A malignant, usually aggressive tumor composed of atypical, neoplastic melanocytes. "In addition, AFF1 is coordinately downregulated in UV-irradiated fibroblasts and in melanoma, and is often dysregulated in cancer." (PMID 23371019, 2013). "In addition, the expression of AFF1, PIM1, PTPN13 and TXNIP was downregulated in UV-irradiated FM SFs with a R87P-CDKN2A mutation, and the expression of these genes was also found to be downregulated in melanoma tissue." (PMID 23371019, 2013).
lung adenocarcinoma (3 papers, 2019 to 2021). A carcinoma that arises from the lung and is characterized by the presence of malignant glandular epithelial cells. "AFF1 inhibits NTS transcription in A549 human lung adenocarcinoma cell line, one of the non-small-cell lung cancer (NSCLC) cell types." (PMID 33493519, 2021). "To dissect the potential roles of AFF1 in lung cancers, we performed RNA sequencing (RNA-seq) transcriptional profiling studies in human lung adenocarcinoma A549 cells after shRNA-mediated AFF1 knockdown." (PMID 33493519, 2021). "Altogether, our results uncovered the NTS-CPS1 regulatory axis, consisting of AFF1 as the master transcription suppressor and IL6 as the antagonist in lung adenocarcinoma cells." (PMID 33493519, 2021). "Thus, our analyses revealed a novel NTS-centered regulatory axis, consisting of AFF1 as a master transcription suppressor and IL6 as an antagonist in lung adenocarcinoma cells." (PMID 33493519, 2021).
Ataxia (2 papers, 2012 to 2018). Ataxia refers to impaired coordination of voluntary muscle movement. "OHC sheep do not exhibit ataxia, but since no other gene in this interval is associated with cataracts, AFF1 is probably the best candidate for the OHC gene." (PMID 22690116, 2012).
colon cancer (2 papers, 2015 to 2024). "However, we did not observe an association between AFF1 rs17703261 with the risk of developing colon cancer." (PMID 26630397, 2015).
lung carcinoma (2 papers, 2021). "In the present study, we found that high expression of AFF1 significantly correlates with better overall survival in lung cancer patients." (PMID 33493519, 2021). "Kaplan–Meier (K-M) plot demonstrated that lung cancer patients with higher expression of AFF1 showed significant longer survival than those with lower expression of AFF1." (PMID 33493519, 2021).
lymphoma (2 papers, 2019 to 2023). A malignant (clonal) proliferation of B- lymphocytes or T- lymphocytes which involves the lymph nodes, bone marrow and/or extranodal sites. "It is also important to highlight that AFF1 locus rearrangements are responsible for many fusion-derived lymphomas in humans." (PMID 37509532, 2023).
osteosarcoma (2 papers, 2022 to 2024). A usually aggressive malignant bone-forming mesenchymal neoplasm, predominantly affecting adolescents and young adults. "For example, our rules show that the AFF1 gene corresponding to the cg12109728 probe is hypermethylated in OS (HG)/high-grade conventional osteosarcoma but relatively hypomethylated in CHORD/chordoma." (PMID 36619306, 2022).
Azoospermia (1 paper, 2025). Absence of any measurable level of sperm,whereby spermatozoa cannot be observed even after centrifugation of the semen pellet. "Interestingly, AFF1 has been linked to heifer conception rate in U.S. Holsteins, whereas DMC1 frameshift mutation causes nonobstructive azoospermia in humans." (PMID 40240941, 2025).